IL4 (interleukin 4)
Diseases named in the same sentence as IL4 in open-access papers (continued):
Sharing a sentence is not in itself a finding about the gene and the disease.
Arthritis (continued). "Simultaneously, the expression of IL-4 in PDCD5 tg mice was higher than their normal control and arthritis control." (PMID 29228993, 2017). "The mice were injected with anti-IL-4, IL-5 or IL-13 blocking monoclonal antibody (mAb) on day 3 before (−3d) and day 3 after (+3d) the second immunization with CII, and the incidence of arthritis was monitored." (PMID 27812008, 2016). "IL-4/IL-13-mediated activation of the STAT6 pathway is also critical to protect bone and cartilage during arthritis." (PMID 27273006, 2016). "Among the cytokines with the greatest importance in inflammatory responses, pain and arthritis, we selected nine cytokines for further study (IFNγ, TNFα, IL1, IL4, IL6, IL10, IL12, IL17 and IL23)." (PMID 26218592, 2015). "We have used the new humanized double-transgenic model of arthritis to test oral administration of the altered peptide ligand A12 peptide and to demonstrate that T cells found in the GALT tissues release IL-10 and IL-4 in response to a murine autoantigen." (PMID 24405551, 2014). "In addition, the arthritis in the anti-IFN-γ group was associated with significantly elevated IFN-γ, IL-4, and IL-17 levels in the joints, whereas the arthritis in the anti-IFN-γ + anti-IL-4 group was associated with significant increase in IFN-γ and IL-4 and a modest increase in IL-17 responses." (PMID 19852819, 2009). "The role of endogenous IFN-γ and IL-4 in the differential regulation of IL-17, leading up to arthritis, was evaluated in experiments involving administration of anti-IL-17 antibody along with anti-IFN-γ or anti-IFN-γ + anti-IL-4 antibodies." (PMID 19852819, 2009). "DBA1/LacJ mice were immunized with type II collagen in complete Freund's adjuvant (CFA) to induce arthritis, and treated with neutralizing antibody to IFN-γ and/or IL-4." (PMID 19852819, 2009). "Our results suggest a detrimental role of IL-4 in GBS sepsis, whereas it plays a beneficial effect on GBS-induced arthritis." (PMID 19606256, 2009). "Mice that received neutralizing antibodies to IFN-γ alone developed an accelerated course of arthritis, and the group that received neutralizing antibodies to both IL-4 and IFN-γ had significantly more severe arthritis than the anti-IFN-γ alone group." (PMID 19852819, 2009). "The ability of A12 to suppress arthritis is correlated with a change in the cytokine response that included combinations of both decreased IFN-γ and increased IL-4 production." (PMID 16982003, 2006). "In earlier studies, we found that adenoviral overexpression of IL-4 resulted in reduced MMP-mediated cartilage damage and chondrocyte death during ICA and arthritis induced by collagen type II." (PMID 15743487, 2005). "IL-4 overexpression in the arthritic knee joint strongly and locally inhibited the mRNA expression of MMP-3 in mice with collagen-induced arthritis." (PMID 15642138, 2005). "More interestingly, we showed a positive linear correlation between serum IL-4 levels and the VAS for arthritis or the DAS28-ESR, and SSc patients with moderate–high joint involvement had statistically significantly higher serum IL-4 levels than SSc patients with a DAS28-ESR ≤ 3.2." (PMID 37763102, 2023). "In vivo, DBA/1J mice with collagen-induced arthritis treated with propolis showed better scores than animals treated only with standard diet, as well as a decrease in the number of IL-17, IFN-γ, and IL-4 secretory cells, suggesting that propolis suppresses the differentiation of Th17 cells." (PMID 37075347, 2023). "Moreover, the peripheral blood CD21low B cell percentage and serum IL-4 and IL-21 levels were positively correlated with the DAS28-ESR and VAS for arthritis." (PMID 37763102, 2023). "Importantly, providing M-CSF/IL-4-treated PBMNCs significantly reduced the progression and the severity of the CFA-induced arthritis, compared to the joints on day 7 (p = 0.016, p < 0.05) and the PBS-treated joints on day 32 (p = 0.017, p < 0.05)." (PMID 36522405, 2022).
Arthritis (continued). "In experimental arthritis animal models, IL-4 treatment reduced the progression of arthritis, including collagen-induced arthritis (CIA), proteoglycan-induced arthritis (PIA), and methylated BSA/IL-1-induced arthritis." (PMID 35163028, 2022). "In line with these human data, genetic deletion of ILC2 in mice aggravated K/BxN serum-induced arthritis whereas expansion of ILC2 by IL-25/IL-33 mini-circles or adoptive transfer of ILC2 from wild-type but not IL-4-/-IL-13-/- mice attenuated arthritis." (PMID 34733292, 2021). "ROS deficient mice are more susceptible to various arthritis models, regardless of the model is mediated by a TH1 (with IFN-γ), TH17 (with IL-17 and IL-23) or even a TH2/IL-13 (with IL-4 and IL-13) type of immune response." (PMID 24358335, 2013). "As both IFN-γ and IL-4 have been shown to suppress IL-17 production, it was possible that the increased severity of arthritis seen in the absence of IFN-γ and IL-4, in comparison to the absence of IFN-γ only, was secondary to higher levels of IL-17." (PMID 19852819, 2009). "Mice in which only IL-4 was neutralized did not have an accelerated course of arthritis, consistent with previous studies." (PMID 19852819, 2009). "Furthermore, the onset and progression of arthritis in the anti-IFN-γ + anti-IL-4 group was faster than in the anti-IFN-γ group and reached a plateau by day 18, when the arthritis score in the anti-IFN-γ group was still increasing." (PMID 19852819, 2009). "Consistent with previous reports, mice that received neutralizing antibody to IL-4 alone did not have an accelerated course of arthritis." (PMID 19852819, 2009). "Consistent with previous data depicting the differences between the systemic and joint specific Th1/Th2/Th17 responses, increased levels of IL-17, IL-4, and IFN-γ were found in the paws of mice which developed accelerated arthritis after receiving IFN-γ neutralizing antibodies." (PMID 19852819, 2009). "Administration of exogenous IL-4 resulted in suppression of CIA, while, in the same experimental model, administration of anti-IL4 monoclonal antibodies augmented both incidence and severity of arthritis." (PMID 19606256, 2009). "Lactobacillus treatment can prevent the onset of arthritis in preclinical models, reduce arthritis scores in CIA rat and pro-inflammatory cytokines (such as IL-17, IL-1β, IL-6, and TNF-α), and increase the release of anti-inflammatory cytokines like IL-4 and IL-10 in bodily fluids." (PMID 40692793, 2025). "However, the relative proportions of IL4-producing cells were significantly higher in WT non-CIA than in WT mice developing arthritis, that would downregulate their immunoreactivity." (PMID 38558087, 2024). "Since BALB/c mice had high expression of IL-4, low expression of IFN-γ, and low production of IgG2a (one-fourth that of IgG2c in C57BL/6NCrSlc mice), IgG1 deficiency did not affect the severity of the arthritis in the BALB/c mice." (PMID 36763580, 2023). "However, SF from patients with early arthritis display increased Th2 cytokines, such as IL-4 and IL-13, but not Th1-related IFN-γ." (PMID 35925523, 2022). "Our group and collaborators demonstrated the successful delivery of IL-4 in vivo using a synovium targeting peptide in the xenograft SCID mouse model, and the selective accumulation of an anti-C5 antibody fused to the same synovium targeting peptide in affected joints of rodent models of arthritis." (PMID 33679801, 2021). "Zymosan caused systemic inflammation with a marked elevation in multiple pro- and anti-inflammatory cytokines TNF-α, IFN-γ, IL-13, G-CSF, M-CSF, IL-6, IL-18, IL-1α and IL-4 in arthritic rats (all arthritis groups pooled) versus the non-arthritic controls (0.001<p<0.05)." (PMID 33878143, 2021). "In addition, compared with arthritis control, PDCD5 tg mice reduced serum levels of the pro-inflammatory cytokines IFN-γ, IL-6, IL-17A and TNF-α and upregulated the expression of the anti-inflammatory cytokine IL-4." (PMID 29228993, 2017).
Arthritis (continued). "These functional relationships suggest that lack of IL-4 may contribute to arthritis in the AF subgroup." (PMID 23092393, 2012). "Similar to the arthritis study, the absence of AnxA1 was associated with evidence of increased allergic inflammation in the OVA-challenged lung, including increased eosinophil recruitment, IL-4 production, and airways dysfunction." (PMID 23230437, 2012). "In mice, the genetic absence of IL-4 leads to more severe arthritis in the CIA model." (PMID 21294892, 2011). "Acetate, propionate: do not have a significant effect on arthritis.Butyrate: inhibits cytokine production (e.g., IFN-g, IL-4) by iNKT cells, thereby attenuating AIA." (PMID 41574450, 2026). "Conversely, blocking Th2 responses with anti‐IL‐4 mAb in nonsusceptible BALB/c mice significantly increased joint swelling, indicating that arthritis severity can be attenuated by Th2 responses." (PMID 39396370, 2024). "While IVIG suppressed arthritis, arthritic inflammation in mice lacking IL-4 was not suppressed by IVIG, indicating that IL-4 was required for the therapeutic effect of IVIG." (PMID 31269967, 2019). "The mice that did not receive anti-IFN-γ antibody (Rat IgG and Control groups) did not develop arthritis by day 21 to 23 and consequently the levels of IFN-γ, IL-4, and IL-17 in the paws remained significantly lower than the mice that received anti-IFN-γ." (PMID 19852819, 2009). "No other arthritis-related cytokines [IL-1β, TNF, IL-17, interferon-γ, IL-4, CCL5 (also called RANTES, for regulated on activation, normal T cell expressed and secreted) and GM-CSF] could be detected in the serum (data not shown)." (PMID 26081345, 2015). "Thus the increased incidence of arthritis in the absence of IFN-γ and IL-4, versus IFN-γ only, does not correlate with further systemic elevation of IL-17." (PMID 19852819, 2009).
malaria (103 papers, 2007 to 2026). Malaria is a serious and sometimes fatal disease caused by a parasite that commonly infects a certain type of mosquito which feeds on humans. "This study investigated gene polymorphisms in the interleukin-4 (IL-4) and its receptor alpha (IL-4Rα) gene regions in human hosts with uncomplicated malaria." (PMID 39482779, 2024). "Interleukin (IL)-4 had been linked to malaria severity, but the findings are controversial, and the evidence is inconsistent and imprecise." (PMID 35820892, 2022). "IL-4 induces Th2 responses and limits both the inflammatory process and Th1 responses, being associated with a protective role in severe forms of malaria." (PMID 34790829, 2021). "CD4+ T cells producing other cytokines such IL-2, IL-10 and IL-4 alone or in combination with the studied cytokines have been shown to be associated with protection from malaria." (PMID 27165269, 2016). "Studies conducted in humans demonstrated that Ag-specific IL-4+ producing T cells were associated with elevated levels of malaria-specific serum IgG and that Th1 cytokines were dominant at acute disease followed by a Th2 response during parasite clearance." (PMID 24453249, 2014). "Of interest, we observed that DBLα-tag–specific CD4+IL-4+ T cells were associated with delayed time to subsequent malaria episode over a period of 1 y, suggesting a possible role for IL-4–secreting CD4+ T cells in protection." (PMID 24453249, 2014). "In this study, we observed a clear association of IL-4–producing T cells specific for DBLα-tags with prolonged time to reinfection and clinical malaria." (PMID 24453249, 2014). "Among the inflammatory mediators implicated in malaria pathogenesis is interleukin (IL)-13, a type 2 cytokine that shares structural and functional characteristics with IL-4." (PMID 23521898, 2013). "This would be in agreement with a previous observation made in malaria-infected individuals, of an association between the activation of IL-4 producing T-cell subsets and the production of antimalarial specific antibodies." (PMID 23668806, 2013). "Malaria and other hemolytic disorders are characterized by enhanced susceptibility to bacterial and viral infections, and increased levels of IL-4, IL-6 and IL-10." (PMID 23358441, 2013). "Studies have established that IL-4 as a key regulator in malaria and three regulatory IL-4 polymorphisms (-590C/T, -34C/T and in intron-3 VNTR) have been shown to regulate serum IL-4 levels, IgG, IgE, disease progression and survival." (PMID 23110190, 2012). "Our study suggests that the IL-4 polymorphisms regulate host susceptibility to malaria and disease progression." (PMID 23110190, 2012). "Studies have documented that elevated antibody IgG and IgE levels against malaria antigens, parasitaemia and malaria susceptibility has been associated with IL-4 -590T allele in several African populations." (PMID 23110190, 2012). "Reports on iron nutrition in children living in malaria endemic areas have indicated some association between IL-4 with all biochemical indices of iron." (PMID 20546583, 2010). "falciparum IgG1 antibody levels seem to be associated with the IL4-590TT genotype in uncomplicated malaria patients with previous malaria experiences (UCME) (P = 0.1219)." (PMID 20003246, 2009). "falciparum IgG antibodies and protection against malaria, while IL4-589T allele was associated with the elevated levels of total IgE in children with severe malaria living in Burkina Faso." (PMID 20003246, 2009). "In individuals carrying the IL4-590 TT genotype with previous malaria experiences, an increased risk of complicated malaria was associated with low anti-P." (PMID 20003246, 2009). "falciparum IgG3 antibody than their IL4-590 counterparts, whereas significantly higher levels were found in uncomplicated malaria patients homozygous for IL4-590 T alleles and with previous malaria experiences." (PMID 20003246, 2009).
malaria (continued). "In particular, complicated malaria patients homozygous for IL4-590 T alleles and with previous malaria experiences exhibited significantly lower levels of anti-P." (PMID 20003246, 2009). "High levels of circulating IL-4 have also been associated with a greater parasite antigen-specific production of IgE in individuals less susceptible to malaria." (PMID 17204149, 2007). "Nonetheless, several other PSGs such as IL4 associated with the control of malaria, one of the most prevalent tropical diseases in Africa was also observed in this study conferring its role of malaria resistance in Nigerian zebu cattle genomes presently in West Africa." (PMID 35428239, 2022). "Our finding of a lower prevalence of placental malaria infection in mothers with either the IL-4−590 or IL-4+33CT and TT genotypes, or still the IL4-TT haplotype, is in accordance with recent results indicating reduced malaria risk in IL4-TT carriers from Indian tribal populations." (PMID 23668806, 2013). "Distribution of IL4 genotypes and alleles in patients with malaria and in asymptomatic controls." (PMID 23110190, 2012). "Several findings have shown association of -590T, -34T and intron-3 VNTR polymorphism R2 with high level of serum IL-4 and consequent high level of total IgG, IgE, anti-plasmodium IgG and IgE, and severity of infection in several populations of malaria endemic region across the globe." (PMID 23110190, 2012). "The IL4-590 gene polymorphism has been shown to be associated with elevated levels of anti-Plasmodium falciparum IgG antibodies and parasite intensity in the malaria protected Fulani of West Africa." (PMID 20003246, 2009). "Thus, the role of IL4-590T allele in regulating antibody profiles and malaria severity is controversial." (PMID 20003246, 2009). "Thus, the diminished peripheral levels of IL-10 and IL-4 in the women with Malaria+CHB may suggest susceptibility to cytokine imbalance (towards Th1)." (PMID 31002731, 2019). "The lesser prevalence of placental parasites in mothers carrying one or two copies of the IL4-TT haplotype was consistent with the higher haemoglobin values (and decreased risk of anaemia) observed in these mothers at delivery, probably due to a lesser impact of malaria-induced anaemia." (PMID 23668806, 2013). "Several polymorphisms affecting IL-4, IL-10, IL-13 genes, lead to changes in cytokine production levels that may impact isotype switching as well as cell interaction and thus be associated with immune-related diseases such as malaria." (PMID 23668806, 2013). "The results suggest that IL4-590C or T alleles participated differently in the regulation of anti-malarial antibody isotype profiles in primary and secondary malaria infection and, therefore, could play an important role in alteration of malaria severity." (PMID 20003246, 2009). "Generally, IL-4 concentrations were significantly higher in the typhoid mono and typho-malaria groups with moderate differences in other groups compared to the control." (PMID 40014608, 2025). "Given that activated basophils are primary sources of the regulatory cytokines IL-4 and IL-13, we sought to examine the contributions of these mediators to basophil-dependent phenotypes in malaria." (PMID 38780542, 2024). "Transforming growth factor-beta regulates the function of other important cells in malaria immunity: Dendritic cells, which produce IL-4 in the acute phase of malaria, T-helper 17 and T regulatory cells." (PMID 38404582, 2024). "It has been suggested that the balance between proinflammatory cytokines and anti-inflammatory cytokines such as IL-4 determines the level of severity in malaria while overproduction of any of the cytokines is also harmful." (PMID 39703208, 2024). "Other cytokines such as IL-4, IL-6, and IL-10 were also elevated in coinfections compared to malaria monoinfection." (PMID 36716305, 2023).